TLR8 (toll like receptor 8)
Diseases named in the same sentence as TLR8 in open-access papers (continued):
Sharing a sentence is not in itself a finding about the gene and the disease.
tumor (continued). "Taken together, our results indicate that IMQ can enhance aerobic glycolysis in tumor cells and that this process is independent of TLR7 and TLR8 expression." (PMID 24658058, 2014). "As the abundance of the TLR4 and TLR8 in tumor cells did not reflect the mRNA levels detected in PBMC we also speculate that local TLR4 and TLR8 may participate in the regulation of tumor growth in NSCLC patients." (PMID 40025339, 2025). "Moreover, despite being a target of TLR8 agonism, we did not see an increase in TLR8 signaling molecules (except MYD88 in dendritic cell populations) in post-treatment biopsies, possibly because of tumor resection timing (scRNAseq)." (PMID 39697344, 2024).
infection (94 papers, 2008 to 2025). The state of being infected such as from the introduction of a foreign agent such as serum, vaccine, antigenic substance or organism. "In the current study, transcriptome analyses indicated that Toll-like receptor (TLR) receptors (Tlr7, Tlr8, and Tlr9) associated with type I IFNs production were significantly upregulated after infection." (PMID 40124358, 2025). "BLaER1 cells, transdifferentiated into monocyte-like cells, as well as primary monocytes deficient for RNASE6 show a dampened TLR8-dependent response upon stimulation with isolated bacterial RNA (bRNA) and also upon infection with live bacteria." (PMID 39363059, 2024). "Polymorphisms and overexpression of TLR8 is associated with pulmonary tuberculosissusceptibility and infection, respectively." (PMID 30237679, 2018). "Several RNA virus associated PRRs, including DDX58, IFIH1, TLR7, and TLR8, were regulated according to infection status, being up-regulated at 24 h pi, and showing little or negligible change in expression during the rest of the study." (PMID 26893019, 2016). "The efficiency of cis infection of DC and subsequent trans infection also involves TLR8 signaling stimulated by HIV-1 encoded ssRNA and DC-SIGN signaling stimulated by gp120." (PMID 24278768, 2013). "There are several stable polymorphisms (SNPs) in the TLR8 gene, one associated with an increased risk of infection in males is rs3764880 (met > val), another target SNP to investigate." (PMID 21619576, 2011). "Our results suggest that TLR7 and TLR8 variants have functional relevance in the setting of HCV-infection by conferring susceptibility to infection." (PMID 22022576, 2011). "Pharmacological TLR8 activation enhances the killing of phylogenetically diverse clinical isolates of drug-susceptible and multidrug-resistant Mtb by macrophages and during in vivo infection in mice." (PMID 40338743, 2025). "Moreover, female individuals carrying the G allele of rs3764879 in TLR8 gene was associated with ASYM infection." (PMID 40531670, 2025). "Moreover, in the same study, patients with GC genotypes of TLR7 (rs3853839) and TLR8 (rs3764879) and AG genotypes of TLR8 (rs3764880) were more susceptible to CHIKV mono-infection." (PMID 37703107, 2023). "Additionally, TLR8 is associated with the cardiac inflammatory responses induced by infection with Coxsackie B viruses." (PMID 31817126, 2019). "In platelets, PLAUR was positively associated with TLR2, TLR4, TLR8, and RIG-I, and with infection these associations changed to TLR7 and LGP2 but continued to correlate with TLR4 and TLR8." (PMID 40825056, 2025). "The anticoagulant PROC associated positively with TLR1 and TLR9, but, with infection, became inversely correlated with TLR2, TLR5, and TLR8." (PMID 40825056, 2025). "In leukocytes, PLAUR positively correlated with RIG-I and MDA5 which changed to TLR3, TLR6, and TLR8 with infection; PLAU, on the other hand, lost its correlation with TLR4 and TLR5 with COVID19." (PMID 40825056, 2025). "We detected fairly high amounts of both TLR7 and TLR8 transcripts, which remained unchanged upon infection." (PMID 39963132, 2025). "These cells recognize viral RNA through recognition receptors such as TLR3, TLR7, and TLR8 and respond to infection by secreting inflammatory cytokines." (PMID 38268832, 2024). "Another example is the pairwise cooperation of TLR8 with TLR7 or TLR9 within endosomal membranes to regulate the eukaryotic inflammatory response upon detection of viral nucleic acids produced during infection." (PMID 39131286, 2024). "Six TLRs recognize the presence of SARS-CoV-2 (TLR2, TLR3, TLR4, TLR7, TLR8, and TLR9), of which TLR2, TLR4, and TLR9 favor the pathogenicity of the virus, while TLR3, TLR7, and TLR8 favor control of the infection and resolution of the disease." (PMID 39062904, 2024). "TLR8 also senses infections with intact, whole bacteria, thus arguing for a physiological contribution to the defense against infections." (PMID 39363059, 2024).
infection (continued). "The most frequent TLR8 polymorphism, TLR8 A1G (rs3764880), has been reported to confer protection against HIV progression, suggesting the role of TLR8 in infection." (PMID 37298575, 2023). "In our study, we observed that the greater the severity of the infection, the greater the expression of TLR8, which is a molecule highly expressed in the lung." (PMID 36366521, 2022). "TLR8 expression was detected in mucosal tissues (skin, gill and intestine) of turbot after infection with Vibrio anguillarum and Streptococcus iniae." (PMID 36439120, 2022). "Although single-PEDV infection showed up-regulation on cell-membrane- (TLR4) and endosomal-associated (TLR3 and TLR8) TLRs by 5 DPI, it seems that these TLRs did exert a sufficient modulatory effect on MyD88 and TRIF." (PMID 36376395, 2022). "In this scenario, recognition of viral RNA by TLR8 prior to substantial tissue damage during infection would contribute mostly to a protective antiviral IFN-mediated response." (PMID 35701499, 2022). "TLR8 signaling mainly induces the activation of NF-κB and plays an important role in antibacterial and antivirus infections." (PMID 34696476, 2021). "Activation of TLR8 with 4 μM CL-75 induced a 50% reduction of the intracellular M. avium burden after 3 days of infection." (PMID 34607464, 2021). "The expression of TLR7 and TLR8 in the lungs of BALB/c mice was upregulated during infections with hMPV, reaching peaks by day 5 p.i.." (PMID 33809875, 2021). "Due to the roles of TLR8 induced by viruses or bacteria, it is of interest to generate the antagonist of TLR8 to counteract the overwhelming immune activation and treat the infection." (PMID 34804111, 2021). "The role of TLR7 and TLR8 SNPs in SRLVs infection surely requires a comparison of infected and uninfected animals." (PMID 34206971, 2021). "In conclusion, this study reveals that ASFV A528R interferes with the phosphorylation and nuclear translocation of NF-κB p65 through its interaction with p65, thereby inhibiting TLR8-NF-κB signaling pathway and its anti-infection function." (PMID 34696476, 2021). "In order to explore the effect of A528R on TLR8-NF-κB mediated anti-infection function, PAMs were transfected with A528R and one ANK deletion mutant, respectively, stimulated with R848, and then infected with either VSV or S. aureus." (PMID 34696476, 2021). "At 6 days after infection, the levels of Tlr7 and Tlr8 in both the brain (P < 0.0001) and the spinal cord (P < 0.01) were higher in WT-infected than in Y114A- or G32S-infected mice." (PMID 32047134, 2020). "Others have shown that TLR8 also contributes in IL-6 production during infection with Streptococcus pyogenes (group A streptococcus, GAS) and Escherichia coli in human myeloid cells." (PMID 31214180, 2019). "Compared to the SISP model, significant changes were only observed for TLR5 and TLR8 mRNA expression by IPEC-J2 cells after C83901 infection, while upregulated TLR8 transcripts were also found in HB101 stimulated IPEC-J2 cells." (PMID 31221216, 2019). "Production of these cytokines was also highly TLR8-dependent during infection with the other bacteria." (PMID 31214180, 2019). "CVB3 can induce TLR7 and TLR8 expression after 48 h of infection at a low multiplicity of infection (MOI)." (PMID 31117206, 2019). "To date, endosomal members of the toll-like receptor (TLR) family including TLR3, TLR7, and TLR8 as well as the cytoplasmic RIG-I-like receptors (RLRs) have been described to sense RNA during infection with a range of viruses." (PMID 29056936, 2017). "In this role, Snapin inhibits HIV‐1 detection by TLR8 in endosomes and subsequently promotes trans‐infection and viral spread through the host." (PMID 28923824, 2017). "Here, we demonstrate that EBV replicates in primary human monocytes several days post-infection (PI), and viral lytic genes strongly induce TLR8 expression and activation of the innate immune response in healthy donor (HD) and SSc monocytes infected with EBV." (PMID 28245863, 2017).
infection (continued). "Inhibition of Snapin enhanced localization of HIV‐1 with TLR8+ early endosomes, triggered a pro‐inflammatory response, and inhibited trans‐infection of CD4+ T cells." (PMID 28923824, 2017). "Lastly, pattern "Yers-Salm" includes 1,694 genes whose expression levels changed preferentially after infection with Y. pseudotuberculosis or S. typhimurium (e.g. TLR8, TGFB1, IL18)." (PMID 26586179, 2015). "We did not detect any statistically significant increase in expression of TLR3, TLR7, and TLR8 transcripts post-infection, however some trends potentially indicating a viral induction were observed (data not shown)." (PMID 24712747, 2014). "TLR7 and TLR8 are PRRs of interest in the setting of HCV-infection as they can bind ssRNAs and lead to the production of large amounts of the antiviral cytokine interferon-α by dendritic cells." (PMID 22022576, 2011). "A different approach for investigating the roles of TLR7 and TLR8 SNPs in the resolution of HCV-infection would require a comparison of patients who are chronically infected with HCV with individuals that have spontaneously cleared infections." (PMID 22022576, 2011). "THP1 differentiated macrophagesdisplayed an increase of TLR8 protein levels after infection with M.bovis BCG." (PMID 18927625, 2008). "A marked increasein TLR8 protein expression was also observed directly in differentiatedmacrophages upon infection with M. bovis bacilleCalmette-Guérin (BCG)." (PMID 18927625, 2008). "Protein expression levels of TLR8 were also shown to increase in macrophagecell lines after infection with BCG." (PMID 18927625, 2008). "Intriguingly, amongst all the TLRs studied, the expression of TLR8 mRNA transcript was most prominently upregulated at 96.6-fold (P < 0.0001) and 120.5-fold (P = 0.0001) following infection by H. pylori J99 and SS1 strains, respectively, implying a potential role of TLR8 in immunity to H. pylori." (PMID 36317079, 2022). "Viral ssRNA entering the cell would colocalize into early endosomes around 15 to 20 min after infection, where the RNA could bind to TLR8." (PMID 35215078, 2022). "The up-regulatory effect on MyD88 and TRIF may be the result of direct viral interaction or the up-regulation effect on cell-membrane- (TLR2 and TLR4) and endosomal-associated (TLR3, TLR8, and TLR9) TLRs induced by single-PDCoV infection." (PMID 36376395, 2022). "Then comes the question, how is TLR8 activated during infection by ASFV which is a DNA virus?" (PMID 34696476, 2021). "Given that IRG1 is needed to control the infection and that CL-75 is a strong IRG1 inducer, we hypothesized that strengthening the activation of TLR8 beyond that of M. avium itself may improve the macrophage control of infection." (PMID 34607464, 2021). "This increased expression suggests that TLR7 and TLR8 may be more relevant than TLR3 in modulating infections with hMPV." (PMID 33809875, 2021). "In addition, TLR8 can also crosstalk with other innate receptors and sense microbial nucleic acids, especially the single-stranded RNA (ssRNA), in infection and immunity." (PMID 34804111, 2021). "Trans-infection of latently infected CD4+ T cells could thus result in reactivation of HIV-1 by activation of the TCR with concomitant TLR8 signaling from endosomal degradation of virus particles." (PMID 31919342, 2020). "This is supported by a recent publication reporting that recognition of bacterial mRNA via TLR8 stimulates follicular helper T cell differentiation by inducing a specific cytokine profile in human monocytes upon infection with live E. coli, thereby promoting vaccine responses." (PMID 30846984, 2019). "In addition, significantly higher expression of TLR6 in CH than in the period prior to infection, TLR8 in AH than in the SLAH/SOI phase, and TLR10 in CH than in AH were apparent in both PBMC and liver biopsies." (PMID 30581424, 2018). "Altogether, these results suggest a role on the TLR8 response in mediating EBV active infection." (PMID 28245863, 2017).
infection (continued). "In support of studies reporting increased susceptibility to infection with AUD, we report down-regulation of a number of genes important for host defense such as cytokines (IL1R1 and TNFSF11), chemokines (CCL2), and receptors (TGFBR1 and TLR8)." (PMID 27427759, 2016). "Interestingly, TLR8 transcriptional levels are increased in patients at the early phase of infection and TLR8 protein expression is increased in macrophages after M. bovis BCG infection." (PMID 23189273, 2012). "Earlier we observed a modest increase of TLR8 and 9 expression during stimulation and infection." (PMID 21827718, 2011). "However, infected macrophagesshowed a marked raise of TLR8 expression at 20 hours post-infection." (PMID 18927625, 2008). "With infection, expression of certain PRRs in platelets increased (TLR9, RIG-I, and CGAS), while in leukocytes, they decreased (TLR6, TLR8)." (PMID 40825056, 2025). "While DENV-2 infection-induced up-regulation of TLR2 and TLR7 mRNA during the early stages of infection (1.5 and 3 h.p.i), the mRNA expression of TLR2, TLR3, TLR4, TLR7, and TLR8 reaches its maximum peak of expression at 24 h.p.i." (PMID 40934228, 2025). "Here, we observed higher TLR2, TLR4, TLR5, TLR6, TLR8, TLR9, Myd88, NLRP3, ASC, and TNF-α mRNA expression at seven weeks after infection by S. mansoni in BALB/c and C57BL/6 mice compared to Swiss mice." (PMID 38896633, 2024). "The addition of agonists to the intracellular TLRs, TLR7, TLR8 and TLR9, prior to infection in PBMCs has been shown to exhibit anti-HIV activity by inducing high levels of the type-1 interferons and interferon-stimulated genes." (PMID 38005883, 2023). "Similar to TLR8, TLR7 mRNA transcript was also increased remarkably at 44.2-fold (P < 0.0001) and 7.8-fold (P < 0.0001) upon J99 and SS1 infection." (PMID 36317079, 2022). "An in vitro infection with hMPV leads to increased expression of TLR7 and TLR8, with peaks at 12 hours p.i., followed by a decreased expression after this time point." (PMID 33809875, 2021). "During primary infection, EBV downregulates TLR7, TLR8, and TLR9 expression to support viral replication in infected B cells." (PMID 31238570, 2019). "Distinct expression patterns of TLR8 and TLR9 have been observed in the mucosal tissues (the intestine, gill, and skin) of turbot after infection with V. anguillarum and Streptococcus iniae." (PMID 30034391, 2018). "After 8-week infection with the pathogen Mycobacterium marinum, the expression of TLR7 in the blood and lymphoid tissues of zebrafish is reduced, whereas the expression of TLR8 is elevated." (PMID 30034391, 2018). "HCV infection induced the expression of TNF-α at two hours post-infection and the simultaneous knockdown of both TLR7 and TLR8 (TLR7/8) impaired this induction." (PMID 26023919, 2015). "When TLR2, TLR7 and TLR8 were silenced, there was a considerable decrease in cytokine secretion in human airway epithelial cells with HRV-6 infection." (PMID 22994237, 2012). "In this male cohort, TLR8–RLR crosstalk was preserved early after ART initiation during acute infection but diminished over time, approaching profiles observed in chronically treated infection." (PMID 41206241, 2025). "Possible molecular targets of miRNA-4634 during infection may include genes such as cyclin-dependent kinase inhibitor 2A (CDKN2A) and Toll-like receptor 8 (TLR8)." (PMID 39795977, 2024). "Interestingly, seven weeks post infection, this pattern shifted, as BALB/c and C57BL/6 upregulated the expression of TLR2, TLR5, TLR8, TLR9, and MyD88 mRNA." (PMID 38896633, 2024). "However, in human monocytes, HIV-1 exposure initially induces autophagy through a TLR8- and BECN1-dependent mechanism, an event that is eventually modulated by the productive infection of the virus." (PMID 35215078, 2022). "TLR-9 RNA in both maternal and foetal placenta and TLR-8 in foetal placenta were not over-expressed at any time after Nc-Spain7 infection." (PMID 32552750, 2020).